ETS1 (ETS proto-oncogene 1, transcription factor)
Diseases named in the same sentence as ETS1 in open-access papers (continued):
Sharing a sentence is not in itself a finding about the gene and the disease.
ovarian carcinoma (continued). "Gemcitabine and cisplatin are commonly used in combination together, and since Ets-1 is involved in cisplatin resistance, further study of the validity of pre-treatment of GSH-depleting agents with gemcitabine and cisplatin combination therapy for ovarian cancer is warranted." (PMID 24238102, 2013). "However, the relationship between Ets-1 and some of its target genes involved in angiogenesis has not been fully investigated in ovarian cancer." (PMID 21439064, 2011). "We have demonstrated that the over-expression of Ets-1 in our ovarian cancer model did not affect protein levels of two closely related ETS family members; however, it is possible that other ETS transcription factors from this very large family also influence cancer metabolism." (PMID 21042593, 2010). "In addition, important cellular modulators, such as non-coding RNAs, Ets-1, CEBPG, ARID1A, SNAI2 and HRD1, could significantly regulate SLC7A11 expression in ovarian cancer cells, suggesting that these modulators could be potential therapeutic targets in ovarian cancer patients." (PMID 38203758, 2024). "Therefore, we speculate that miR-206 has no direct effect on KRT80, but through ETS1 which is a direct target of miR-206 in ovarian cancer cells." (PMID 34659572, 2021).
prostate carcinoma (37 papers, 2011 to 2025). A carcinoma that arises from epithelial cells of the prostate gland. "And the overexpression of Ets1 were always associated with malignant biological features of prostate cancer." (PMID 32984354, 2020). "ETS1 is up-regulated in prostate cancer and can promote tumor growth and metastasis by regulating genes involved in cell migration, invasion, and angiogenesis." (PMID 39364872, 2025). "In prostate cancer, ETS-1 expression is often higher compared to normal prostate tissue, correlating with disease progression and prognosis." (PMID 40181983, 2025). "Silymarin inhibits the expression of ALDH1A1 in prostate cancer, which in turn inhibits the further activation of RARα and Ets1." (PMID 39055491, 2024). "ALDH1A1 promotes the invasion and metastasis of prostate cancer by activating RARα, which further activates Ets1." (PMID 39055491, 2024). "Studies have shown a positive correlation between ALDH1A1 expression in prostate cancer tissue and Recombinant retinoic acid receptor alpha (RARα) and Erythroblastosis-twenty six 1 (Ets1)." (PMID 39055491, 2024). "While over half of prostate cancers display fusions involving the oncogenic ETS transcription factors (including ETS1), ETS1 has been described in several patients with prostate cancer involved in fusion with HERV-K17 and HERV-K_22q11.3." (PMID 36979914, 2023). "ETS1 promotes epithelial-to-mesenchymal transition and enhances transforming growth factor signaling in prostate cancer cells." (PMID 35463077, 2022). "By directly inhibiting E26 transformation specific‐1 (ETS1), miR‐129 controlled the survival, proliferation, migration, and invasion of prostate cancer cells." (PMID 34029007, 2021). "ALDH1A1 promoted invasion and metastasis of prostate cancer by activating the RARα, which further activates Ets1." (PMID 32984354, 2020). "Our findings are in some ways different from similar studies performed in prostate cancer cells, where the number of ETS1 bound elements are significantly smaller compared to those in the SCC25 cells." (PMID 31306413, 2019). "A recent report has shown that ETS1 knockdown in DU145 prostate cancer cells activates dual specificity phosphatase 4 (DUSP4), DUSP6, and sprouty RTK-signaling antagonist 4 (SPRY4)." (PMID 28474232, 2017). "We then investigated the possibility that cell necrosis mediated by the inhibition of PARP-1 concomitant with Ets-1 accumulation was due to an increase in DNA damage as observed with Ets fusion proteins in prostate cancer and Ewing's sarcoma." (PMID 23405229, 2013). "The overexpression of Ets1 is closely related to the deterioration of prostate cancer." (PMID 39055491, 2024). "Therefore, TPX2 enhanced the activation of the HGF/ETS-1 pathway to enhance the invasion of endocrine-independent prostate carcinoma cells and thus it would be a promising target for prostate carcinoma treatment." (PMID 34123781, 2021). "Moreover, the expression of tpx2 or ets-1 is much higher in the metastatic prostate carcinoma than in primary prostate carcinoma." (PMID 34123781, 2021). "Next, the correlation between tpx2 with mmp3, mmp9 or ets-1 in prostate carcinoma was examined." (PMID 34123781, 2021). "NR2F2 (COUP-TFII) plays a critical role in mediating the effects of DHA treatment on EFNB2, EBF1, ETS1, and VEGFA expression, and the knockdown of NR2F2 can recede the functional changes induced by DHA treatment in prostate cancer cells." (PMID 39364872, 2025). "On the other hand, endocrine resistance and prostate cancer pathways are highlighted by genes such as MDM2 and LEF1, Oncogene-induced senescence, and MDM2 and ETS1." (PMID 40621499, 2025). "In prostate cancer cell lines SK1 knockdown (KD) has significantly changed expression of several genes including downregulation of NSUN2, G3BP2 and upregulation of ETS1." (PMID 30971929, 2019).
prostate carcinoma (continued). "The SLFN11 promoter contains several ETS binding sites and functions as an ETS factor response gene, with ETS transcription factors FLI1 and ETS1 having proposed roles in regulating SLFN11 expression in colon, breast, and prostate cancers." (PMID 28212573, 2017). "Our approach has yielded 11 transcription factors that show strong cancer-specific transcriptional activation of targets, including the novel candidates KAT2A and TRIM28, alongside established drivers of prostate cancer MYC, ETS1, GABP and YY1." (PMID 28592290, 2017). "The mRNA expression level of tpx2 or ets-1 was much higher in prostate carcinoma than it was in prostate non-tumor tissues." (PMID 34123781, 2021). "Our results indicated that Silybin showed inhibition of prostate cancer and the mechanism was involving with downregulating ALDH1A1 expression, thereby inhibiting the activation of RARα and preventing the activation of Ets1 to inhibit the growth and invasion of prostate cancer." (PMID 32984354, 2020). "Collectively, these results indicated that Silybin could inhibit prostate cancer by downregulating the expressions of ALDH1A1, RARα and Ets1 in vitro." (PMID 32984354, 2020). "We found that ETS1 shares these characteristics, indicating that it is a transcriptional amplifier that enhances productive RNAPII elongation in ECs and possibly other cell types in which it is expressed, including blood and prostate cancer cells." (PMID 28851877, 2017). "Human prostate cancer PC-3 cells, which are AR negative and ETS-1 positive, were co-transfected with EBS-Luc, AR vector, or empty vector." (PMID 29312607, 2017). "In addition, ETS1 positively regulated CIP2A expression in PC-3 and LNCaP prostate cancer cell lines." (PMID 21445343, 2011). "This reveals binding sites for several known prostate cancer regulatory TFs, including AR, ERG, ETS1 and FOXA1 in a putative enhancer region that does not belong to the set of GWAS SNPs." (PMID 37971305, 2024). "Likewise, a recent study demonstrated that ETS1, but not ETS2, is necessary for cell migration after RAS/MAPK activation in DU145 prostate cancer cells." (PMID 28474232, 2017).
gastric cancer (35 papers, 2007 to 2025). A primary or metastatic malignant neoplasm involving the stomach. "PancEts-1 is transcribed from the promoter region of the ETS-1 gene and is associated with poor survival in gastric cancer patients." (PMID 32722129, 2020). "PancEts-1 levels were positively correlated with those of ETS-1 in gastric cancer specimens, associated to poor outcome for patients." (PMID 32722129, 2020). "Mechanistically, pancEts-1 facilitated the physical interaction between NONO and Ets related gene (ERG), resulting in increased ERG transactivation and transcription of Ets-1 associated with gastric cancer progression." (PMID 29773901, 2018). "Herein, we identified Ets-1 promoter-associated noncoding RNA (pancEts-1) as a novel lncRNA associated with the gastric cancer progression via mining of publicly available datasets and rapid amplification of cDNA ends." (PMID 29773901, 2018). "In this study, through mining of public datasets and performing rapid amplification of cDNA ends (RACE), we identified Ets-1 promoter-associated noncoding RNA (pancEts-1) as a novel 1395-nt lncRNA associated with poor survival of gastric cancer." (PMID 29773901, 2018). "In gastric cancer, the v-ets erythroblastosis virus E26 oncogene homolog 1 (Ets1) had been implicated in tumor development and progression, in part by trans-activating MMPs-1 and -9." (PMID 24670365, 2014). "Importantly, the tumorigenicity of gastric cancers was significantly suppressed by restoring miR-9 expression in miR-9-deficient gastric cancers, thereby reducing the expression of the cyclin D1 and Ets1 oncogenes." (PMID 25717380, 2014). "However, the mechanisms underlying the Ets1 over-expression in gastric cancer still remains largely unknown." (PMID 23383271, 2013). "Functional validation demonstrated that ETS1 actively suppresses EFNA4-mediated tumor suppression in gastric cancer, establishing a novel inhibitory axis in GC pathogenesis." (PMID 41162582, 2025). "ETS-1 contributes to gastric cancer progression by promoting cell proliferation, inhibiting apoptosis, and facilitating migration and invasion." (PMID 40181983, 2025). "Research indicates that ETS-1 expression is significantly elevated in gastric cancer tissues compared to normal gastric mucosa and is strongly associated with the pathological stage, lymph node metastasis, and patient prognosis." (PMID 40181983, 2025). "In gastric cancer, ETS1 expression correlated significantly only with the presence of lymph node metastasis." (PMID 39941022, 2025). "Propofol inhibited the proliferation and invasion of gastric cancer cells by regulating the circPVT1/miR-195-5p/ETS1 axis, but enhanced the apoptosis of gastric cancer cells." (PMID 39314750, 2024). "ETS1 expression, on the other hand, has only marginal prognostic value in a variety of cancers, including gastric cancer (GC)." (PMID 35463077, 2022). "miR-383 is a tumor suppressor that inhibits cell proliferation, metastasis, and EMT in BC via targeting ETS1, which can also suppress cell cycle progression in gastric carcinoma cells through regulating Cyclin E2 expression." (PMID 36131343, 2022). "Meanwhile, current studies showed that miR-9 inhibited gastric cancer and miR-512-5p impaired non-small cell lung cancer proliferation through targeting ETS1." (PMID 33999777, 2021). "LncRNA pancEts-1 directly interacts with NONO to increase its interaction with ERG, resulting in transactivation of ERG, increase of Ets-1 expression, and promotion of the tumorigenesis and aggressiveness of gastric cancer cells." (PMID 29773901, 2018). "Our previous evidence shows that Ets-1 levels are elevated in gastric cancer, and knockdown of Ets-1 inhibits the invasiveness and metastasis of gastric cancer cells." (PMID 29773901, 2018). "We validated higher transcript levels of pancEts-1 and Ets-1 in an independent cohort of 81 primary gastric cancer specimens, than those in normal gastric mucosa (P < 0.0001)." (PMID 29773901, 2018).
gastric cancer (continued). "Stable transfection of pancEts-1 or sh-pancEts-1 #2 led to significantly increased and decreased Ets-1 expression in gastric cancer cells, which was abolished by transfection of sh-NONO or NONO, respectively." (PMID 29773901, 2018). "The ERG expression was positively correlated with that of Ets-1 in these gastric cancer specimens (R = 0.760, P < 0.001)." (PMID 29773901, 2018). "Higher pancEts-1 levels were detected in gastric cancer cases with metastasis (P < 0.0001) or high Ets-1 immunostaining (P < 0.0001)." (PMID 29773901, 2018). "Epigenome-wide DNA methylation arrays have also identified the role of DVL2 and ETS1 methylation in diffuse- and mixed-types of early gastric cancers." (PMID 28418867, 2017). "It has been suggested that ETS1 plays an important role in regulating gastric cancer cell invasion, metastasis, and angiogenesis." (PMID 26897165, 2016). "The critical epigenetic regulator miR-23b exhibits a tumor-suppressive effect on gastric cancer progression through targeting Notch2 receptor and Ets1." (PMID 26041881, 2015). "The relationship between levels of miR-23b and Notch2 receptor, E2F1, and Ets1 mRNAs in the tumor samples from 21 gastric cancer patients was analyzed using the Pearson correlation analysis." (PMID 26041881, 2015). "Mechanistically, miR-23b suppressed tumor progression and pluripotency gene expression and affected tumorsphere ultra-structure in gastric cancer cells via targeting Notch2 receptor or Ets1." (PMID 26041881, 2015). "We detected the downregulation of has-miR-9 in gastric cancer, which suppressed the proliferation, invasion, and metastasis of gastric cancer cells through targeting cyclin D1 and Ets1." (PMID 24982669, 2014). "To investigate the direct effects of miR-9 on the expression of cyclin D1 and Ets1 in gastric cancer cells, we performed the miRNA over-expression experiments." (PMID 23383271, 2013). "Ectopic expression or knockdown of miR-9 resulted in responsively altered expression of cyclin D1, Ets1 and their downstream targets phosphorylated retinoblastoma and matrix metalloproteinase 9 in cultured gastric cancer cell lines SGC-7901 and AGS." (PMID 23383271, 2013). "Lower miR-9 expression was observed in gastric cancer tissues with higher immunostaining of cyclin D1 (P<0.0001) or Ets1 (P<0.0001)." (PMID 23383271, 2013). "In this study, miR-9 was found to be down-regulated and inversely correlated with the expression of cyclin D1 and v-ets erythroblastosis virus E26 oncogene homolog 1 (Ets1) in gastric cancer tissues and cell lines." (PMID 23383271, 2013). "In contrast, higher cyclin D1 and Ets1 transcript levels were detected in gastric cancer tissues (P<0.0001 and P<0.0001, respectively)." (PMID 23383271, 2013). "In this study, we demonstrate, for the first time, that miR-9 directly targets cyclin D1 and v-ets erythroblastosis virus E26 oncogene homolog 1 (Ets1), and suppresses the proliferation, invasion and metastasis of gastric cancer cells in vitro and in vivo." (PMID 23383271, 2013). "In this study, we demonstrated that as a direct target of miR-9, Ets1 was up-regulated in gastric cancer and contributed to the migration and invasion of cancer cells." (PMID 23383271, 2013). "ETS-1 plays a significant role in the development and progression of gastric cancer." (PMID 40181983, 2025). "EFNA4 is highly expressed in early gastric cancer, whereas ETS1 expression is low." (PMID 41162582, 2025). "In fact, ETS1 and TCF4 expression are significantly upregulated in advanced gastric cancer tissues, suggesting that ETS1 and TCF4 may be involved in tumor growth and progression." (PMID 34686186, 2021). "The luciferase test results suggest that the CRISPReader can significantly activate the expression of luciferase in BGC-823, RPMI 1640, and HGC-27 gastric cancer cell lines that highly express Ets-1, while it cannot express luciferase in normal gastric epithelial cells GES-1." (PMID 34124154, 2021).
gastric cancer (continued). "However, the mechanisms contributing to high expression of Ets-1 in gastric cancer remain to be determined." (PMID 29773901, 2018). "Notably, the expression levels of ERG (R = 0.649, P < 1.0 × 10−4) or NONO (R = 0.644, P < 1.0 × 10−4) were positively correlated with those of Ets-1 in gastric cancer specimens." (PMID 29773901, 2018). "Notably, the pancEts-1 levels were positively correlated with those of Ets-1 in gastric cancer specimens (R = 0.733, P < 1.0 × 10-4)." (PMID 29773901, 2018). "It was found that Notch2 pathway and Ets1 contribute to gastric cancer progression and metastasis." (PMID 26041881, 2015). "MiR-145 was found to directly target the 3'-UTR of Ets1-mRNA and overexpression or knockdown of this miRNA altered both the mRNA and protein levels of Ets1 and those of MMPs-1 and -9 with subsequent inhibition of invasion, metastasis, and angiogenesis of gastric cancer cells." (PMID 24670365, 2014). "Since above results indicated the negative regulation of cyclin D1 and Ets1 expression by miR-9, we hypothesized that knockdown of cyclin D1 and Ets1 might exert similar effects on cultured gastric cancer cells." (PMID 23383271, 2013). "In addition, our data confirmed that miR-9 directly targeted cyclin D1 and Ets1 in gastric cancer cells through 3′-UTR luciferase reporter assay." (PMID 23383271, 2013). "This study extends our knowledge about the regulation of cyclin D1 and Ets1 at the post-transcriptional level by miRNA, and suggests that miR-9 may be of potential values as a novel therapeutic target for gastric cancer." (PMID 23383271, 2013). "The immunoreactivity of cyclin D1 and Ets1 was significantly higher in gastric cancer cases with deeper gastric wall invasion (P<0.001 and P = 0.001), lymph node metastasis (P<0.001 and P<0.001), distant metastasis (P<0.001 and P<0.001), and advanced TNM stage (P<0.001 and P = 0.004)." (PMID 23383271, 2013). "Furthermore, anti-miR-9 inhibitor promoted the proliferation, migration and invasion of gastric cancer cells, while knocking down of cyclin D1 or Ets1 partially phenocopied the effects of miR-9 over-expression." (PMID 23383271, 2013). "In this study, we demonstrated that over-expression of miR-9 attenuated the proliferation, migration and invasion of gastric cancer cells, which was similar to that of cyclin D1 or Ets1 knockdown, suggesting the potential application of miR-9 as a target for the therapeutics of gastric cancer." (PMID 23383271, 2013). "Previous studies indicate that Ets1 expression is related to the clinicopathological features of gastric cancer, including tumor infiltration and lymph nodes or distal metastasis, suggesting its critical role in the invasion and metastasis of gastric cancer." (PMID 23383271, 2013). "ETS1, together with other transcription factors including AP-1, NF-κB, and HNF3β, has binding sites in the promoter of claudin 9 gene, and aberrant activity may lead to deregulation of tight junctions in gastric cancer." (PMID 41425714, 2025). "High levels of pancEts-1, NONO, ERG, or Ets-1 were respectively associated with poor survival of gastric cancer patients, whereas simultaneous expression of all of them (HR = 3.012, P = 0.105) was not an independent prognostic factor for predicting clinical outcome." (PMID 29773901, 2018). "In addition, we identify that pancEts-1 is essential for the interaction between NONO and ERG, which results in ERG transactivation and Ets-1 upregulation that are associated with gastric cancer progression." (PMID 29773901, 2018). "However, whether lncRNAs contribute to the upregulation of v-ets erythroblastosis virus E26 oncogene homolog 1 (Ets-1), an established oncogenic protein facilitating tumor invasion and metastasis, in gastric cancer remains elusive." (PMID 29773901, 2018).